BDNF (brain derived neurotrophic factor)
Diseases named in the same sentence as BDNF in open-access papers (continued):
Sharing a sentence is not in itself a finding about the gene and the disease.
Anxiety (continued). "Since IBD is associated with an increased risk for anxiety and mood disorders, we focused in particular on three messenger molecules that are known for their role in the regulation of anxiety and mood: NPY, BDNF, and CRF." (PMID 25414650, 2014). "Additionally, the BDNF Met/Met homozygous PDMs displayed higher anxiety during the menstrual phase compared with the Val carrier PDMs." (PMID 25383981, 2014). "This hypothesis is corroborated by animal studies in which Met/Met homozygotes exhibited defective activity-dependent BDNF secretion from neurons and manifested anxiety-related behaviors in stressful settings." (PMID 25383981, 2014). "Transgenic mice that are Met carriers of BDNF Val66Met exhibit increased anxiety-related behaviours under stress conditions, as well as decreased BDNF levels in the hippocampus, in line with the ‘neurotrophic hypothesis’." (PMID 24433458, 2014). "In contrast, there is a clear link between anxiety-related behavior and BDNF signaling." (PMID 24795586, 2014). "Combined with evidence that GABA-signaling influences emotionality, it is possible that the sexually dimorphic effect of BDNF signaling on anxiety-depressive-like behavior could be mediated through effects on GABA-related gene expression." (PMID 24062698, 2013). "One explanation could be that BDNF HET mice show increased anxiety which could lead to an increase in startle amplitude." (PMID 24155701, 2013). "Data from studies of whole brain and/or hippocampus largely show that a decrease in the level of BDNF, and by extension TrkB, generally leads to an increase in depressive- and anxiety-related behaviors or in females, a lower threshold for stress-induced anhedonic behavior." (PMID 24369067, 2013). "Mecamylamine was demonstrated to be a useful augmentation agent to SSRI treatment of major depression, and administration of mecamylamine also appears capable of blocking dexamethasone-induced anxiety, which occurs concurrently with upregulation of BDNF levels." (PMID 23785661, 2013). "It has been hypothesized that P4 protects the brain after injury by up-regulating brain derived neurotrophic factor (BDNF), a neurotrophin known to promote survival of neurons and play a role in cognition, anxiety-like behavior and pain." (PMID 23781171, 2013). "CREB is an important step in BDNF signaling and a point of convergence of signaling pathways regulating synaptic activity and anxiety such that the effects of n-3 increasing CREB activation may be significant for modulation of synaptic plasticity." (PMID 23483949, 2013). "Evidence also suggests that BDNF may be a mediator of the anxiety reducing effects of antidepressant medications." (PMID 23630504, 2013). "Exposure to neonatal stress can reduce expression of hippocampal BDNF via altering gene expression, which may facilitate vulnerability to mood and anxiety as consequence of decreased neuronal survival." (PMID 23785661, 2013). "In addition to this, the authors also showed that immunization of T cells with a CNS-related peptide reduced the stress-induced anxiety and restored levels of BDNF, shown to be important for stress resilience." (PMID 24312102, 2013). "However, studies also found that increases in BDNF through communal nesting induced an anxiety phenotype by reducing latency to immobility and increasing immobility time in the forced-swim test (FST)." (PMID 23847583, 2013). "The findings suggested that the effects of reduced amygdaloid BDNF expression on ethanol preference and anxiety-like behaviors may be mediated by the downstream regulation of Arc." (PMID 23584115, 2012). "Additionally, these animals exhibit increased anxiety-like behaviors and significant reductions in hippocampal glucocorticoid receptors as well as BDNF and serotonin receptor mRNA." (PMID 24961305, 2012).
Anxiety (continued). "In an extension of these findings, investigators used an animal model of genetic predisposition to alcoholism and anxiety (i.e., selectively-bred alcohol-preferring [P] and nonpreferring [NP] rats) to study the role of BDNF in the extended amygdala." (PMID 23584115, 2012). "In contrast, a more sustained up-regulation of BDNF in the BLA may underlie the pathological increase in fear and anxiety observed following stress." (PMID 22272355, 2012). "For instance, both anxiety and BDNF are increased 1 and 21 days after CIS." (PMID 22272355, 2012). "Accordingly, elevated cytokine levels observed in the hippocampus of db/db mice may contribute to decrease BDNF level and consequently to impair anxiety-like behaviors and spatial cognitive performances." (PMID 21949705, 2011). "In previous findings hippocampal BDNF levels were correlated with anxiety." (PMID 20862278, 2010). "Since alterations in BDNF expression were also found in response to emotions such as anxiety or fear in rodents and BDNF affects emotional preferences in humans, it remains to be determined how the stress itself or the associated behavioral responses contribute in mediating these changes." (PMID 20074340, 2010). "Here, we report that PRS has different, sometimes opposite, effects in male and female rats in terms of spatial learning, anxiety, expression and activity of group-I and group-II mGlu receptors in the hippocampus, hippocampal BDNF levels, and adult neurogenesis in the hippocampal dentate gyrus." (PMID 18478112, 2008). "Overall, human data strikingly parallel animal data on BDNF rolein memory and anxiety." (PMID 17502911, 2007). "Furthermore, models of anxiety show that BDNF and apoptosis are closely related." (PMID 41009813, 2025). "Interestingly, the 2D projections of the samples using the two first components reinforce the relation between parasite load and increased serum NO levels and oxidative levels (TBARS) in brain areas, and these variables were correlated with the decrease of BDNF expression and anxiety (EPMT)." (PMID 41237192, 2025). "Moreover, IL-4Rα inhibition was associated with downregulation of anti-inflammatory cytokines, upregulation of TNF-α and nitric oxide, and altered BDNF expression, collectively contributing to cognitive dysfunction and exacerbated neuroinflammation and anxiety-like behaviours." (PMID 40977748, 2025). "In rodent models, exogenous NPS reduces anxiety- and fear-like behaviours, speeds fear-memory extinction, stabilises the hypothalamic-pituitary-adrenal axis, enhances dopaminergic tone and elevates hippocampal brain-derived neurotrophic factor (BDNF)-changes concordant with symptom relief." (PMID 40758097, 2025). "The biochemical parameters such as BDNF, Angiotensin II, cortisol, lipid profile, and questionnaires to assess psychological parameters such as quality of life and sleep, emotional quotient, mental state, happiness, anxiety, and stress were assessed pre and post intervention." (PMID 39916293, 2025). "However, the percentage of distance traveled in the center tends to decrease significantly in the group of mice with BDNF overexpression, which may indicate a correlation between BDNF expression and an increase in anxiety (Test 2)." (PMID 39408863, 2024). "Thus, we could conclude that increased expression of the mature form of BDNF in the neonatal mPFC is involved in increased anxiety and depressive-like behavior in adolescence." (PMID 39619203, 2024). "Furthermore, the results of OFT and EPM indicated that the mice exhibited anxiety-like behavior after BDNF pathway was inhibited, which suggested that BDNF pathway may be involved in regulating learning and memory ability and emotionality in mice." (PMID 38570868, 2024).
Anxiety (continued). "The conduction of the experiment with female rats could be a subject of future research, as memory, anxiety levels, as well as the BDNF and Cyclin D1 expression, can be influenced by the natural fluctuations in the sex hormone levels during the ovarian cycle in female rats." (PMID 39727966, 2024). "Our results showed that tobacco smoke exposure for 36 days caused an upregulation in NF-κB expression and a downregulation in BDNF expression in the HIP and the HYP of rat brains, and these changes might be the cause of smoking withdrawal anxiety-like behavior induction." (PMID 39195700, 2024). "Notably, anxiety behaviors induced by chronic social defeat stress are associated with decreased expression of the SERT, MAO-A, and brain-derived neurotrophic factor (BDNF) genes in the raphe nucleus." (PMID 39595020, 2024). "Therefore, the fundamental physiology of BDNF in anxiety should be further studied." (PMID 38672038, 2024). "AAV-BDNF transduction and selective overexpression of BDNF in the cortical neurons of Sip1wt/fl mice promotes the activation of their exploratory and motor functions and suppression of anxiety, and thus, such individuals are better adapted to the conditions of a changing environment." (PMID 39408863, 2024). "Hence, it is reasonable to suggest that increased BDNF may be related to the observed reduction in anxiety-like behaviors in germ-free mice." (PMID 38756771, 2024). "Similarly, we observed a significant decrease in synaptic signaling proteins including GAP 43 and BDNF, which may be a reason why anxiety‐like behavior increased in treatment groups." (PMID 36942730, 2023). "Thus, we may infer that the degree of anxiety‐like behaviors in mice is closely related to the decreased expression of BDNF, although further experiments are needed to explore the more detailed mechanism of action." (PMID 37118929, 2023). "However, in RHA rats, TP, which induces a proactive behavior aimed at removing the clamp from the tail but not anxiety-like behaviors [4 and present study], is also associated with alterations in BDNF signaling that are not present upon FS." (PMID 37298449, 2023). "Given the role of BDNF in brain plasticity, memory, and learning, we can conclude that levels of BDNF at different developmental stages may influence resilience and vulnerability to anxiety during those developmental stages." (PMID 35998298, 2023). "Likewise, hippocampal BDNF overexpression ameliorates the anxiety of animals." (PMID 37239153, 2023). "Thus, we hypothesized that serum BDNF and state/trait anxiety were valuable as predictive indicators for changes in somatic symptoms in PD patients." (PMID 37533888, 2023). "Furthermore, the BDNF overexpression alleviated anxiety as assessed using different tests." (PMID 37239153, 2023). "However, the relationship of BDNF levels in subjects with anxiety symptoms treated with auriculotherapy remains unknown." (PMID 38055476, 2023). "Mechanisms by which FS might cause the development of the disease include FS-mediated decreases of brain-derived neurotrophic factor (BDNF) and induction of low-grade inflammation, as well as addiction-like effects with signs of behavioral depression and anxiety after sugar withdrawal." (PMID 36205767, 2023). "Thus, running wheel access may be protective against an anxiety phenotype generated by the BDNF allelic variation." (PMID 35625351, 2022). "BDNF, acting through the TrkB, is thought to be a critical mediator of fear learning, and amygdala TrkB activation is required for the consolidation of stable extinction memories, which is involved in the pathophysiology of psychiatric diseases, including anxiety and mood disorders." (PMID 35466212, 2022). "Likewise, while the rs6265 SNP of BDNF was associated with anxiety in gastric cancer patients, such association did not appear to exist in prostate cancer patients." (PMID 35528795, 2022). "Furthermore, inhibitors that block overexpressed BDNF have been shown to reduce anxiety." (PMID 35203954, 2022).
Anxiety (continued). "Thus, this study was designed to evaluate the effects of minocycline in comparison to those of memantine, an NMDA antagonist, on locomotion and anxiety-like behaviour, phosphorylated tau protein levels, and BDNF and CREB protein expressions in the mPFC of LPS rats." (PMID 36362262, 2022). "Alterations in BDNF expression may affect anxiety-related behaviors." (PMID 35203954, 2022). "Therefore, we suggest that the functional disruption of the HIP induced by reduced BDNF expression may be closely related to anxiety-like symptoms." (PMID 35722162, 2022). "It was found that supplement with sesamol improved anxiety induced by inflammatory bowel disease through repairing synaptic impairments, upregulating the expression levels of norepinephrine and serotonin, increasing BDNF levels via the BDNF/TrkB/CREB signaling pathway." (PMID 36358502, 2022). "Therefore, BDNF-TrkB neurotrophic signalling pathway may play a role in mediating the anti-anxiety effect of α-asarone." (PMID 36545308, 2022). "RA patients with anxiety (p = 0.003), receiving biologics (including etanercept, adalimumab, golimumab, abatacept, tocilizumab, tofacitinib, and rituximab) (p = 0.01), retired (p = 0.006), and had a disease duration of more than 5 years showed significantly lower serum level of BDNF." (PMID 33673283, 2021). "Therefore, stimulation at HT7 was closely related to the anti-anxiety effect of BDNF." (PMID 33919862, 2021). "Additionally, infusion of BDNF into the central amygdala normalizes Arc levels and attenuates the onset of the withdrawal-related anxiety, suggesting that BDNF-Arc signaling in the central and medial amygdala is involved in alcohol dependence and anxiety related to drinking behavior." (PMID 34909648, 2021). "However, the impact of increased BDNF levels on anxiety in this study is unclear." (PMID 33767622, 2021). "Therefore, fatty acid profile that promotes endothelial function for BDNF production, may have a protection role against psychological disorders, including stress and anxiety." (PMID 32377214, 2020). "In a stressful environment, variant BDNF mice (BDNF (Met/Met)) showed anxiety, and this anxiety could not be reversed by fluoxetine." (PMID 32185198, 2020). "The prefrontal cortex and hippocampus play an important role in anxiety, and they are cooperating during anxiety, being mediated by the corresponding receptors on the neuron membrane, resulting in the onset of numerous essential signaling pathways, like the BDNF signal pathway." (PMID 32655658, 2020). "Moreover, when BDNF is low, it fails to stimulate synaptic growth of serotonergic neurons in the brain, and low levels of serotonin are associated with anxiety." (PMID 32839416, 2020). "Therefore, SWHP could protect the prefrontal cortex and hippocampus in the anxiety rats by promoting the expression of BDNF, resulting in corresponding antianxiety effects." (PMID 32655658, 2020). "Therefore, SWHP may protect the prefrontal cortex and hippocampus from anxiety rats by promoting the expression of BDNF, resulting in corresponding antianxiety effects." (PMID 32655658, 2020). "Interestingly, BDNF levels were positively correlated with the time spent in the center of the open field raising the possibility that levels of BDNF in the PFC may play a role in programming anxiety-like behavior in juvenile male rats." (PMID 32793001, 2020). "We did not choose a model with >50% cortical BDNF reduction because mice with complete postnatal depletion of BDNF from the nervous system develop anxiety-like behavior, hyperactivity, freezing, and a clasping phenotype that might otherwise mask an effect on corticostriatal motor skill learning." (PMID 32651187, 2020). "Thus, BDNF could reduce depression and anxiety by stimulating synaptic growth of serotonergic neurons in the brain." (PMID 32839416, 2020).
Anxiety (continued). "Furthermore, the combined treatments of fluoxetine and treadmill exercises have been shown to alleviate PTSD animals' anxiety responses, inhibit the hypothalamus-pituitary-adrenal gland stress system, increase hippocampal brain-derived neurotrophic factor levels, and decrease apoptosis biomarkers." (PMID 33299494, 2020). "In some reports, a lower serum BDNF level was associated with a greater risk to develop panic symptoms, and with an inadequate treatment response, but other authors did not support BDNF as a biomarker for panic attacks." (PMID 32824625, 2020). "However, epilepsy did reprogram the anxiety/BDNF relationship." (PMID 31331937, 2019). "Furthermore, it has been demonstrated that alterations in BDNF expression may affect anxiety-related behavior, although the neural circuitry involved in these processes remains to be exactly defined." (PMID 31281833, 2019). "And the BDNF released from presynaptic vesicles into the synaptic cleft, dependent intracellular calcium concentration, were prevented in the neuron which might lead to the anxiety." (PMID 29896126, 2018). "Both spatial memory and anxiety might be affected by the level of BDNF." (PMID 30618659, 2018). "An animal study demonstrated the effect of sex hormones on BDNF; female BDNFMet/Met transgenic mice exhibited significant fluctuations in anxiety-like behaviors over the estrous cycle; specifically, these mice exhibited increased anxiety-like behaviors during the estrus phase." (PMID 29867348, 2018). "Additionally, the production of BDNF mediates the anxiety induced by drug withdrawal." (PMID 29896126, 2018). "Based on this background, the present study hypothesized that changes in synaptic ultrastructure, which could be induced by a reduction of BDNF due to an increase in HCN1 expression in the Hip and NAc, might be associated with ethanol withdrawal-induced anxiety." (PMID 29896126, 2018). "The current investigation examined whether raising male mice in an enriched environment (EE) would modulate social and anxiety-like behaviors in early adulthood and influence brain expression of pro-inflammatory cytokines and brain-derived neurotrophic factor (BDNF)." (PMID 30065637, 2018). "Thus, the female and male F1 offspring from mothers and/or fathers who had been restrained for 60 days showed significantly reduced levels of anxiety-like behavior and of serum cortisol but increased levels of hippocampal GR and BDNF mRNA expression, compared to offspring from unstressed parents." (PMID 28000794, 2016). "Thus, evidence from studies in animal-model studies shows, at best, that the precise relationship between BDNF and anxiety is still unknown." (PMID 25932008, 2015). "The link between an abnormal BDNF system and anxiety vulnerability may be through the hippocampus." (PMID 26257661, 2015). "Moreover, BDNF deletion mutants are more vulnerable to stress, as shown by hypothalamo-pituitary axis hyperactivity, impaired working memory and increased depressive-like and anxiety-like behavior." (PMID 25932008, 2015). "Central administration of BDNF also reduces anxiety-like behaviors and normalizes aberrant sexual preference and social behaviors in prenatally alcohol exposed male mice born to dams also exposed to stress, suggesting that altered BDNF levels might affect these types of behaviors." (PMID 24961305, 2012). "Thus, treatment with HDAC inhibitors appears to have similar effects on withdrawal-induced anxiety as BDNF, and acute ethanol exposure may have similar effects on histone acetylation and BDNF levels." (PMID 23584115, 2012). "The primary outcomes will include depressive (BDI-II) and anxiety (GAD-7) symptoms, perceived stress (PSS-10), cognitive performance (NIH Toolbox), and plasma brain-derived neurotrophic factor (BDNF)." (PMID 41753948, 2026).